CEBPA (CCAAT enhancer binding protein alpha)
Diseases named in the same sentence as CEBPA in open-access papers (continued):
Sharing a sentence is not in itself a finding about the gene and the disease.
acute myeloid leukemia (continued). "Expression of CEBPA protein was increased in HCCs, and epigenetic aberrations in regulating CEBPA expression contributed to leukemic transformation in acute myeloid leukemia." (PMID 28423525, 2017). "Of note, mutations in several of the genes that confer leukemia predisposition (e.g., CEBPA, ETV6, GATA2, NF1, RUNX1, PTPN11, CBL, and RAS) are also frequently found in sporadic acute myeloid leukemia (AML) or myelodysplastic syndrome (MDS)." (PMID 29326930, 2017). "CCAAT/enhancer-binding protein-α (CEBPA) is a critical regulator of myeloid differentiation whose inactivation contributes to the development of acute myeloid leukemia (AML)." (PMID 26053097, 2015). "CCAAT/enhancer-binding protein-α (CEBPA) is crucial for normal granulopoiesis and is frequently disrupted in acute myeloid leukaemia (AML)." (PMID 20628397, 2010). "Finally, we found that OAS3 was observably related with some mutation types (CEBPA, FLT3 internal tandem duplication, NRAS, and EVI1 expression) in patients with acute myeloid leukemia (LAML)." (PMID 41700140, 2026). "Wang et al48 linked TET1 expression to M0/M1 morphology and nucleophosmin 1 (NPM1) mutations, correlating with worse survival rates, particularly in acute myeloid leukemia without CCAAT enhancer binding protein alpha (CEBPA) mutations." (PMID 40520993, 2025). "However, the reverse downstream gene, CEBPA, is a key factor involved in the significant inhibition of the disease and function-related signaling pathways in acute myeloid leukemia signaling." (PMID 40297811, 2025). "CEBPA is a key factor of the acute myeloid leukemia signaling pathways, which may be significantly inhibited by KCP, as observed by the traditional IPA bioinformatics pathway analysis." (PMID 40297811, 2025). "Moreover, in cases of acute myelogenous leukaemia, FOXC1 knockdown induces the loss of repressor proteins, the gain of CCAAT Enhancer Binding Protein Alpha (CEBPA) binding and the upregulation of nearby genes." (PMID 38429902, 2024). "Furthermore, in a human acute myeloid leukemia study, patients that had defective CEBPA double mutants had increased Ire1a expression." (PMID 38392328, 2024). "Mutations that reduce long isoform expression are frequently seen in acute myeloid leukemia (AML), including mutations in CEBPA itself that occur in 10–15% of these cancers, emphasizing that the stoichiometry of these two isoforms must be maintained for proper differentiation." (PMID 38803235, 2024). "The role of CEBPA was first established in acute myeloid leukemia (AML)." (PMID 34970478, 2021). "CEBPA-related diseases, include leukemia, acute myeloid leukemia, and myeloid leukemia." (PMID 32038705, 2019). "The first two pathways that are worth mentioning are associated (i) with the ErbB receptor signaling and (ii) with genes (c-KIT, STAT3, AKT3) that have been mainly described as increased in acute myeloid leukemia, in which the crucial role of CEBPA has been widely demonstrated." (PMID 26496024, 2016). "Disruption of CEBPA function contributes to the development of acute myeloid leukemia (AML)." (PMID 25252716, 2014). "CCAAT/enhancer-binding protein α (CEBPA) is detected in approximately 10% of patients with acute myeloid leukemia (AML)." (PMID 40805192, 2025). "Acute myeloid leukemia (AML), for example, has over 20 known molecular subtypes, arising from specific genetic alterations such as NPM1 mutations, FLT3-ITD, CEBPA mutations, and various chromosomal rearrangements." (PMID 40940796, 2025). "Homoharringtonine, a kind of alkaloid, could be regarded as the inhibitor of CEBPA, because it could repress the synthesis of CEBPA and decrease CEBPA protein levels, which may possibly be the mechanism of Homoharringtonine in CEBPA-double-mutant acute myeloid leukemia." (PMID 38227591, 2024).
acute myeloid leukemia (continued). "Because of its role in cell cycle inhibition and cellular differentiation, abnormal CEBPA function or regulation is often found in acute myeloid leukemia (AML), liver cancer, breast cancer, and lung cancers." (PMID 34039742, 2021). "The CCAAT/enhancer-binding protein-α (CEBPα) is a crucial transcription factor for normal hematopoiesis and cell cycle that frequently disrupted in human acute myeloid leukemia (AML)." (PMID 29911120, 2018). "The CCAAT/enhancer-binding protein-α (CEBPα) is a crucial transcription factor for normal hematopoiesis that frequently disrupted in human acute myeloid leukemia (AML)." (PMID 29911120, 2018). "To date, the CEBPA c.690G>T SNP (rs34529039) was analyzed only in acute myeloid leukemia (AML) patients, where it occurred with a frequency ranging from 3.6% to 32%, and was described as a non-pathogenic alteration." (PMID 27602952, 2016). "Various mechanisms have been identified as to how CEBPA function is dysregulated in patients with acute myeloid leukemia (AML)." (PMID 22676581, 2012). "For hematological malignancies, hereditary predisposition was first identified in chronic lymphocytic leukemia (CLL) and acute myeloid leukemia (AML), which has led to the identification of several germline mutations, such as RUNX1, CEBPA, GATA2, ANKRD26, DDX41 and ETV6 mutations." (PMID 36998465, 2023). "In acute myeloid leukemia (AML), METTL3 promotes leukemogenesis and inhibits myeloid differentiation, potentially through the targeting of oncogenic genes such as MYC and CEBPA." (PMID 38012755, 2023). "In patients with acute myeloid leukemia, SOCS1 expression is negatively correlated with mutant CEBPA." (PMID 36832783, 2023). "Studies have reported its high expression in acute myeloid leukemia (AML), promoting cellular transformation and proliferation by the post-transcriptional regulation of ASB2, RARA, MYC, and CEBPA." (PMID 36371254, 2022). "Understanding the function and full characteristics of CEBPA and c-MYC genes in the group of patients with acute myeloid leukemia can be particularly helpful in assessing prognosis, and their usefulness as prognostic factors can be revealed." (PMID 33170359, 2020). "In osteogenesis and adipogenesis and in acute myelogenous leukemia, hypermethylation of the CpG islands at the proximal promoter region of CEBPA silences C/EBPα transcriptionally." (PMID 30599048, 2019). "For acute myeloid leukemia the panel is composed of FLT3ITD/FLT3-TKD, NPM1, C-KIT, PTPN11 and CEBPA." (PMID 23863689, 2013). "Both the World Health Organization and the European Leukemia Net classifications have included molecular markers such as NPM1, FLT3 and CEBPA as a prognostic factor for cytogenetically normal-acute myeloid leukemia (CN-AML) reinforcing their importance in cytogenetics." (PMID 23941109, 2013). "For patients with acute myeloid leukaemia (AML), myeloid maturation in FTL3-ITD positive AML cells appears to be partially suppressed by a feedback loop between TOPK and the transcription factor responsible for granulocyte differentiation, CEBPA." (PMID 30356039, 2018). "In human acute myeloid leukaemia (AML), CEBPA function is frequently disrupted." (PMID 20628397, 2010). "In acute myeloid leukemia (AML), oncogenic CCAAT/enhancer binding protein-α ((C/EBPα)-p30) is a dominant negative isoform of the tumor suppressor C/EBPα that is generated by CEBPA mutations." (PMID 32258027, 2020). "TRIB2 has previously been identified as an oncogene that causes acute myelogenous leukemia via inactivation of the transcription factor, CEBPA (CCAAT/enhancer-binding protein alpha); however, to date there is no established relationship of TRIB2 with chemo-resistance." (PMID 29312632, 2017). "In human acute myeloid leukemia (AML) cell line models, 1,25-dihydroxyvitamin D3 induces monocytic differentiation and CD14 expression, an effect that is mediated through activation of MEF2C signaling via regulation of CCAAT-/enhancer-binding protein alpha (CEBPA)." (PMID 26487643, 2015).
acute myeloid leukemia (continued). "Moreover, CEBPA-dependent expression of Fms related receptor tyrosine kinase 3 (FLT3) renders acute myeloid leukemia cells vulnerable to ferroptosis upon inhibition of FLT3, suggesting a therapeutic potential for targeting this pathway in acute myeloid leukemia treatment." (PMID 38844964, 2024). "CEBPA is identified as an exclusive transcription factor displaying a positive correlation with FTO and regulating its transcription in acute myeloid leukemia (AML)." (PMID 31142332, 2019). "GATA2, CEBPA and CSF1R have been reported in MDS and acute myeloid leukemia (AML)." (PMID 27959900, 2016).
leukemia (144 papers, 2006 to 2026). A malignant (clonal) hematologic disorder, involving hematopoietic stem cells and characterized by the presence of primitive or atypical myeloid or lymphoid cells in the bone marrow and the blood. "Together, the overall findings from WTS provide a strong rationale to diagnose this patient’s leukemia as AML with CEBPA mutation." (PMID 39975890, 2025). "CEBPA mutations, all single allelic, appeared in four cases, further supporting their potential role in this leukemia subtype." (PMID 41155189, 2025). "Together, WTS findings strongly support diagnosing this patient’s leukemia as AML with CEBPA mutation." (PMID 41057686, 2025). "N‐terminal mutations in CEBPA are known to have a penetrance close to 100% of leukemia development; however, they correlate with a favorable prognosis." (PMID 39118233, 2024). "Recently, a therapeutic strategy for the treatment of CEBPA-mutated leukemia with DNA-hypomethylating agents has been suggested." (PMID 36232714, 2022). "WT1 mutations are frequently found in de novo AML, especially in younger patients and in FLT3-ITD or CEBPA mutated leukemias." (PMID 33917307, 2021). "The combination of mutations produced maturation arrest, similar to CSF3R/CEBPA mutant murine leukemia." (PMID 31784538, 2019). "Here, we show that reducing Myb activity can override the differentiation barrier, although the dependency on Myb expression generally observed in leukaemia is minimal in the presence of CEBPA biallelic N-terminal mutations." (PMID 30877232, 2019). "LL cells were used to represent AML harbouring biallelic N-terminal CEBPA mutations, whereas cells carrying one K mutation and one L mutation (KL cells) provided a model of leukaemia with both N- and C-terminal CEBPA mutations." (PMID 30877232, 2019). "In the present study, we have investigated the requirement for the transcription factor Myb in the maintenance of CN-AML driven by different combinations of CEBPA mutations in comparison with leukaemia characterised by the expression of wild-type C/EBPα." (PMID 30877232, 2019). "Mutations in the CEBPA gene are frequently associated with leukaemia, being found in 8–14% of all de novo AML with normal karyotype and typically involve both alleles." (PMID 30877232, 2019). "Mutations in several other germ line leukemia predisposition genes (CEBPA, GATA2, ETV6) were also rare or undetected." (PMID 29326930, 2017). "Sporadic mutations in CEBPA (monoallelic or biallelic) have been reported 5–14% of individuals with AML, and among those whose leukemias have biallelic mutations, germline CEBPA mutations were found in about 11.1% of patients." (PMID 29270394, 2017). "In the first class, oncogenes (RUNX1, FLT3, LEF1) or tumor suppressors (RUNX1, CEBPA) implicated in leukemia were selected." (PMID 24786086, 2014). "A second somatic mutation in CEPBA is common in patients with germline CEBPA associated leukemia." (PMID 39278810, 2024). "Therefore, the identification of C/EBPα-DDIT3 axis as a regulator of UPR signaling during myeloid differentiation helps us better understand the physiological mechanisms by which HSPCs with CEBPA deficiency avoid leukemia transformation." (PMID 38475919, 2024). "Furthermore, we have also demonstrated that the dependency on Myb generally observed in leukaemia is attenuated in a murine model of AML that is driven by biallelic CEBPA N-terminal mutations." (PMID 37996430, 2023). "This investigation was carried out in order to answer the question whether CEBPA gene expression level has any association with clinic-pathological features and influences the process of leukemia development/progression in individuals with ALL." (PMID 31666608, 2019). "Compared with cells expressing wild-type C/EBPα, which show a proliferation and differentiation response to enforced reduction in Myb levels, leukaemia driven by biallelic CEBPA mutations exhibits distinct phenotypic responses that are reflected in changes in gene expression." (PMID 30877232, 2019).
leukemia (continued). "N- and C-terminal CEBPA mutations exert distinct biological roles in leukemia initiation." (PMID 31784538, 2019). "These regions of UPD seemed to be non-random and may be used to unmask pre-existing recessive mutations in leukemia genes, such as CEBPA, WT1, FLT3 and RUNX1." (PMID 18221515, 2008). "Collectively, these results indicate that the acute induction of ATF4-regulated pathways can selectively induce cell death of p30-expressing cells, and suggest that this could be exploited as a vulnerability to treat leukemia patients with N-terminal CEBPA mutations." (PMID 40221437, 2025). "Specifically, R-2HG inhibited FTO activity, thereby increasing global m6A RNA modification and reducing the stability of MYC/CEBPA transcripts in R-2HG-sensitive leukemia cells, showing antitumor activity." (PMID 41362736, 2026). "Consistent with our pooled screening results, KRAB-mediated repression of the CEBPA +42 kb cisRE resulted in decreased CEBPA expression and maintained leukemia cells in a CD34+ stem cell–like state following MECOM degradation." (PMID 40991835, 2025). "A total of 100 TFs with silenced promoters were downregulated relative to AML, including hematopoietic regulators and genes known to be involved in leukemia, such as CEBPA, CEBPD, KLF4, IRF4 or MEIS1." (PMID 38972954, 2024). "These molecular categories also showed intercategorical similarities, forming large clusters of AMKL/AEL, immature AML, CBF leukemias, CEBPA and two clusters demarcated by HOXA and HOXB gene expression." (PMID 38212634, 2024). "These molecular categories also showed inter-categorical similarities, forming large clusters of AMKL/AEL, immature AML, CBF leukemias, CEBPA, and two clusters demarcated by HOXA and HOXB cluster gene expression." (PMID 37398194, 2023). "Categories with acute megakaryoblastic or erythroid leukemia (AMKL/AEL) phenotypes are clearly enriched in infants, whereas CBF leukemias and mutation-defining leukemias (e.g., UBTF, NPM1, CEBPA) were enriched in adolescents and young adults." (PMID 37398194, 2023). "We have previously demonstrated the requirement for Myb in the maintenance of murine CEBPA-driven leukaemia and that the dependency on Myb expression is dictated by the nature of the mutations that drive the leukaemic phenotype." (PMID 37996430, 2023). "CHAF1B is essential for normal hematopoiesis, whereas its overexpression promotes leukemia by binding chromatin at discrete sites and interfering with the occupancy of CCAAT enhancer binding protein alpha (CEBPA)." (PMID 36035173, 2022). "It has been shown that YTHDF2 targets a plethora of mRNAs for degradation in cancers, such as, TNFR2, c-Myc and CEBPA in leukemia, EGFR, IL11, SERPINE2 and SOCS2 in liver cancer, and PD-1, CXCR4, and SOX10 in melanoma." (PMID 33658012, 2021). "On the example of the CEBPA gene locus, silenced by DNA methylation in the leukemia model used herein, we carried out a molecular and biological dissection of the potential mechanism implicated in NAD-induced demethylation." (PMID 34831209, 2021). "Another reader, YTHDF2, was found to bind c-Myc and CEBPA mRNAs to enable m6A modification in the 5′-UTR and CDS, promoting c-Myc and CEBPA mRNA stabilization and leukemia cell proliferation." (PMID 32316617, 2020). "R-2HG exhibits broad antiproliferative effects in high-FTO leukemia via targeting FTO/MYC/CEBPA signaling." (PMID 31921664, 2019). "This is consistent with data from MLL-rearranged leukemias, where CEBPA is requisite for entrance into the myeloid lineage and leukemia initiation." (PMID 31784538, 2019). "Mutations in other common leukemia-related genes such as nucleophosmin 1 (NPM1), CCAAT/enhancer-binding protein alpha (CEBPA), and Wilms tumor 1 (WT1) have been found to occur as both preleukemic and late events." (PMID 29164062, 2017). "CEBPA was found initially to regulate normal hematopoietic developmental pathways and its abnormalities were identified in leukemia." (PMID 29312632, 2017).